CASC22 (cancer susceptibility 22)
Synonyms: TCONS_00024290; LincRNA-ENST00000515084; LINC01373; LOC107983961
Gene: Long non-coding RNA gene on chromosome 16 (52,258,517 to 52,280,638, forward strand). Ensembl gene ENSG00000260887.
Diseases named in the same sentence as CASC22 in open-access papers:
CASC22 is named in the same sentence as 1 disease in open-access papers, as found by Europe PMC text mining. Sharing a sentence is not in itself a finding about the gene and the disease.
CASC22 shares sentences with these, for which no sentence is quoted: breast carcinoma (1 paper).